INS (insulin)
Diseases named in the same sentence as INS in open-access papers (continued):
Sharing a sentence is not in itself a finding about the gene and the disease.
Insulin resistance (continued). "Under physiological conditions, leptin improves hepatic insulin sensitivity, suppresses glucose production, and increases peripheral glucose uptake, whereas hyperleptinemia or leptin deficiency is usually associated with hyperglycemia and insulin resistance." (PMID 38203600, 2023). "Although previous studies have established a connection between NC and various risk factors, such as obesity, metabolic syndrome, insulin resistance, and insulin clearance, there is still a gap in understanding its potential to predict cardiovascular events as a composite outcome." (PMID 37123795, 2023). "On the other hand, LEP can cause insulin resistance by affecting insulin secretion." (PMID 37239168, 2023). "Hypersecretion of insulin and hyperinsulinemia could occur prior to insulin resistance and contribute not only to T2D but also the risk of CVD." (PMID 37200851, 2023). "In hyperthyroidism, impaired glucose tolerance may be the result of mainly hepatic insulin-resistance, whereas in hypothyroidism the available data suggests that the insulin resistance is associated with impaired insulin actions on peripheral tissues." (PMID 36830883, 2023). "In addition, obese subjects with high levels of uric acid have been found to have lower insulin sensitivity than obese subjects with normal uric acid levels, which further implies an association between hyperuricemia and insulin resistance." (PMID 37238228, 2023). "Generally, weight gain is associated with increased insulin resistance and higher insulin levels." (PMID 38139760, 2023). "In addition, the PI3K/AKT pathway is indispensable in the insulin signaling pathway and is associated with obesity and the severity of insulin resistance." (PMID 36980960, 2023). "Insulin resistance, defined as decreased responsiveness to the metabolic actions of insulin, has been widely blamed for MetS and its individual risk factors, driving the European Group for the study of Insulin Resistance (EGIR) to propose the term insulin resistance syndrome for MetS." (PMID 36673133, 2023). "Loss of or diminished insulin sensitivity is one of the symptoms of insulin resistance." (PMID 37445928, 2023). "Therefore, these participants displayed elevated insulin levels, representing a greater risk of developing insulin resistance, and ultimately, an increase in susceptibility to T2DM." (PMID 36986139, 2023). "This genetic insulin resistance may explain the associations observed among NT‐proANP, insulin resistance and fasting insulin, and thigh SAT and PMAT in EA participants." (PMID 36905117, 2023). "Importantly, DNL in WAT is associated with improved insulin sensitivity and therefore counteracts obesity-induced insulin resistance." (PMID 38264660, 2023). "Additionally, the HFD led to increases in TC, TG, LDL, VLDL, glucose, and cardiovascular-related risk factors, such as AI, AC, CRR, and CAI, liver mass, insulin, and insulin resistance." (PMID 37107470, 2023). "Furthermore, adipocytes co-cultured with Pparg−/− ATMs show inhibition of insulin-stimulated glucose uptake, directly showing causality of macrophage Pparg deficiency and adipose insulin resistance." (PMID 36994095, 2023). "Insulin resistance in skeletal muscles, liver, and pancreas may be caused by defects in glucose transporter and/or insulin signaling, while beta cell dysfunction is caused by oxidative stress, and high fatty acid content." (PMID 36819346, 2023). "Moreover, they found that SOCS1 and SOCS3 inhibit insulin signaling and cause insulin resistance by inhibiting insulin receptor substrate 1 (IRS1) and IRS2 binding to the insulin receptor in cultured L6 myotubes and 3T3L1 adipocytes." (PMID 36609306, 2023). "There is growing evidence that a process analogous to peripheral insulin resistance occurs in the brains of PD patients, which suggests that loss of insulin signaling may contribute to the development of the pathological features of PD1." (PMID 36707543, 2023).
Insulin resistance (continued). "Indeed, several studies have reported that the deficiency of M1 macrophages enhances insulin sensitivity in obese mice, whereas deletion of M2 macrophages results in insulin resistance in wild-type (WT) mice." (PMID 36838843, 2023). "Indeed, type 2 diabetes is a chronic age‐related disease characterized by an inability to control blood glucose homeostasis, caused either by a decreased insulin action (insulin resistance) or inadequate insulin release by pancreatic β‐cells." (PMID 37060190, 2023). "The combination of insulin resistance, insufficient insulin secretion, and excessive glucagon secretion can cause T2DM and may lead to micro- and macrovascular complications." (PMID 37630716, 2023). "Besides, the development of type 2 DM has more recently been linked to vitamin D deficiency, which has been linked to increased insulin resistance and reduced insulin secretion." (PMID 38022364, 2023). "We proposed the mechanism by which ZFYVE28 is involved in insulin signaling and provided a potential therapeutic target to improve insulin sensitivity and prevent metabolic and cardiovascular diseases associated with insulin resistance." (PMID 37884540, 2023). "Since T2D development is associated with dysfunction in beta cells and insulin resistance, many studies have focused on the insulin signal transduction pathway, some of which have identified dysregulated lncRNAs, indicating their potential regulatory role in insulin signal transduction." (PMID 37218990, 2023). "Moreover, MMP, MEP, MiBP, MECPP, and MEOHP have also been linked to fasting blood glucose and insulin, and insulin resistance index, which are parameters related to GDM." (PMID 37367903, 2023). "Adiponectin, an anti-inflammatory adipokine secreted from adipose tissue also promote recruitment of GLUT-4 to the plasma membrane, thereby maximizing insulin’s ability to mediate glucose uptake, while a low level of adiponectin is associated with obesity, insulin resistance and T2DM." (PMID 37447192, 2023). "Previous reports revealed that high intakes of fiber as an important component of DDRRS, along with low dietary GI, can reduce T2D risk by reducing fasting plasma glucose and insulin level, improving glycemic control, and reducing insulin resistance and obesity." (PMID 37316867, 2023). "For longstanding T1DM, insulin resistance to exogenous insulin may worsen, which may be associated to some degree with body weight." (PMID 37630716, 2023). "Because high insulin demand arising from insulin resistance may be one of the underlying reasons for β-cell failure, treatment strategies that can increase insulin sensitivity are desired." (PMID 37514025, 2023). "As insulin sensitivity is reduced, especially in skeletal muscle, mTOR signaling which has been implicated in insulin resistance and obesity pathogenesis contributes to the development of the inflammatory process by stimulating the activation of the NfᴋB pathway." (PMID 36902158, 2023). "T2DM is a complex disease that may be attributed to insulin resistance, impaired insulin secretion, increased glucose production, and genetic causes." (PMID 37007365, 2023). "Elevated plasma/serum uric acid is associated with an increased risk of insulin resistance, and pathogenic mechanisms may be related to the inhibition of insulin signaling and AMPK activity." (PMID 38053726, 2023). "Vitamin D deficiency is hypothesized to cause insulin resistance via several pathways, including increased proinflammatory cytokines, reduced insulin production by pancreatic beta cells, and decreased glucose absorption in peripheral tissues." (PMID 37324274, 2023). "Physical activity increases the sensitivity to insulin, during muscle contraction, the skeletal muscle enhances glucose uptake into the cells and reduces intra-abdominal fat, which is known as a risk factor for both insulin resistance and obesity." (PMID 37373398, 2023).
Insulin resistance (continued). "However, the underlying mechanism by which probiotics decrease insulin resistance or increase sensitivity to insulin for glucose uptake requires further study." (PMID 37040355, 2023). "The pathogenesis of T2DM is characterized by the inflammatory component inducing progressive loss of β-cell insulin secretion with co-existing insulin resistance, impacting early β-cell function and cell fate, where overweight and obesity are deemed the most effective “accelerator”." (PMID 37152942, 2023). "This insulin resistance phenomenon results from an alteration in the insulin-responsive signaling pathway caused by ectopic lipid accumulation, thus demonstrating the crucial importance of insulin in the regulation of glucose homeostasis." (PMID 37628901, 2023). "Considering the intricate relationship between insulin resistance and the pathogenesis of Alzheimer’s disease, it is plausible that serum biomarkers associated with insulin metabolism might display irregularities in individuals affected by dementia." (PMID 38105338, 2023). "However, T2DM can also occur inversely before obesity in some individuals with inherent insulin resistance resulting in increased hepatic glucose production and elevated insulin levels, which are the actual cause of obesity." (PMID 37152942, 2023). "The MTNR1B rs10830962 G allele also increased the risk of GDM, and in women homozygous for the rs10830962 G allele, physical activity decreased maternal fasting insulin and insulin resistance (according to the homeostatic model assessment of insulin resistance, HOMA-IR)." (PMID 36974476, 2023). "Additionally, a previous study demonstrated that saturated and short-chain TG species were reduced after a weight loss program, and this change was directly associated with an increase in insulin sensitivity among individuals with insulin resistance." (PMID 36902372, 2023). "Whether muscle mitochondrial dysfunction is a cause or consequence of insulin resistance is still controversial, although there is evidence that targeting mitochondria specifically can improve insulin action." (PMID 36137277, 2023). "Basal BVRA protein levels are positively associated with fasting insulin and indexes of increased insulin resistance and insulin secretion, such as HOMA-IR, HOMA-β, and the insulinogenic index, a validated indicator of acute beta cell response (first-phase insulin secretion: (BI30-FBI0)/(BG30-FBG)." (PMID 37108445, 2023). "These phenomena cause reduction of insulin secretion and increase in insulin resistance." (PMID 37842314, 2023). "Many individuals with type 2 diabetes may have some degree of insulin resistance and may also have a relative deficiency in insulin production by the pancreas." (PMID 37274075, 2023). "At 2 years of intervention, low-protein diet responses significantly interacted with lower genetic risk score and greater decreases in fasting insulin, HbA1C, insulin resistance, and a lesser increase in β cell function, compared to those with a higher genetic risk score." (PMID 37610590, 2023). "These shrunk adipose tissues in BRSK2-overexpressing mice might be attributed to the acute insulin resistance caused by massive insulin secretion, consistent with the phenomenon caused by the insulin receptor antagonist S961." (PMID 37188647, 2023). "Recent in vivo evidence has also shown that reducing circulating insulin levels may protect and reverse adiposity, insulin resistance, and hyperglycemia that is associated with obesity." (PMID 37025414, 2023). "However, while genes linked to insulin resistance and inflammation predominate in females, genes linked to insulin secretion predominate in males." (PMID 37291636, 2023). "L-asparaginase has been shown to cause subclinical impairment of insulin secretion, and glucocorticoids have been associated with multiple mechanisms including β cell damage, decreased insulin synthesis, increased insulin resistance, and increased gluconeogenesis." (PMID 40303251, 2023).
Insulin resistance (continued). "For instance, the genetic variant rs757343 has been observed to be associated with the severity of the PCOS phenotype (but not an increased risk for PCOS), while variants in the Cdx2 and DHCR7 genes are associated with insulin resistance and insulin sensitivity in PCOS." (PMID 37251667, 2023). "In addition, the ratio showed significant associations with all markers of insulin resistance/insulin sensitivity studied (fasting and 2-h insulin, AUCi, HOMA-IR, and Matsuda index)." (PMID 37188859, 2023). "The long-term higher hyperglycemia of diabetic patients is mainly caused by the defect of insulin secretion or the impaired biological function of insulin (insulin resistance), which leads to the occurrence of serious complications and the dysfunction of the main organs." (PMID 37514488, 2023). "Although insulin deficiency and insulin resistance are implicated in the development and progression of bone loss, studies elucidating the effects of insulin treatment on bone health yielded heterogeneous outcomes, either having beneficial or negligible effects." (PMID 37569816, 2023). "In contrast, dietary fiber may reduce prostate cancer risk by decreasing carbohydrate absorption to reduce insulin resistance and improving insulin sensitivity." (PMID 37299507, 2023). "The GCKR risk allele that increased liver fat content was founded to be associated with lower FPG, fasting insulin, and homeostatic model assessment for insulin resistance (HOMA-IR), but higher plasma low-density lipoprotein cholesterol (LDL-C), triglycerides, and 2-h postprandial glucose levels." (PMID 37711901, 2023). "It was hypothesized in these studies that there is a well-established association between insulin sensitivity and blood pressure, with fasting insulin possibly serving as a crude marker for the metabolic abnormalities associated with insulin resistance." (PMID 38054122, 2023). "In patients with PCOS, insulin resistance may be associated with mitogenesis and/or metabolic abnormalities in insulin target tissues." (PMID 37796920, 2023). "Furthermore, systemic insulin resistance (i.e., increased fasting blood glucose and insulin levels) is increasingly implicated in the pathophysiology of PH." (PMID 38074873, 2023). "Also ovariectomy caused central adiposity, hyperglycemia, high serum insulin representing insulin resistance in agreement with our previous report." (PMID 37488554, 2023). "Furthermore, hyperglycemia will cause a compensatory increase in insulin secretion from pancreatic β cells to counter the insulin resistance." (PMID 36836874, 2023). "However, lactate production is higher in IR (by about ten times), as observed in those with type 2 diabetes and generally in insulin resistance, underling insulin’s possible role." (PMID 37367840, 2023). "Additionally, ART has been associated with enhanced insulin sensitivity, which can help mitigate the risk of developing insulin resistance and metabolic disorders." (PMID 37719547, 2023). "Both DM2 and CHD are caused by impaired insulin signaling and subsequent insulin resistance." (PMID 37832109, 2023). "The physiological mechanism of insulin resistance owes to deficient insulin action at target cells." (PMID 37664840, 2023). "PTDM has many of the same characteristics as type II DM, including insulin resistance, hypertriglyceridemia, hypertension, low-grade inflammation, obesity, and decompensated insulin release; however, the underlying mechanisms might be different." (PMID 36831005, 2023). "While insulin resistance and impaired insulin secretion are the two main pathophysiological mechanisms for the development of T2D, T1D is characterized by absolute insulin deficiency due to progressive destruction of insulin-producing pancreatic beta cells." (PMID 36983200, 2023).
Insulin resistance (continued). "Elevation of phenylalanine and its derivatives (1-carboxyethylphenylalanine) could contribute to progression of insulin resistance as phenylalanine stimulates insulin secretion, potentially causing hyperinsulinemia." (PMID 37175541, 2023). "It is acknowledged that skeletal muscle is the primary organ responsible for whole-body insulin-mediated glucose utilization, and a reduction in glucose disposal caused by the loss of skeletal muscle mass may further result in insulin resistance." (PMID 38115119, 2023). "However, the high-fat/sucrose diet caused hyperinsulinemia, insulin resistance and reduced insulin sensitivity." (PMID 36674448, 2023). "Associations of various adipokines with insulin resistance, but also with increased insulin sensitivity, increased systolic blood pressure, and atherosclerosis, highlight the significance of adipokines in several components of metabolic syndrome and metabolic diseases in general." (PMID 37239090, 2023). "One study of a variant in the patatin-like phospholipase-3 (PNPLA3)/adiponutrin gene (rs738409 C.G) found that carrying the G allele (n = 96) compared with being a CC homozygote (n = 104) was associated with lower fasting insulin, insulin resistance, and LGA132." (PMID 38110524, 2023). "The prospective association of CRP with increased insulin resistance and reduced adjusted insulin secretion hint to the role of inflammation in the development of impaired metabolism after GDM and could be used as an early marker for risk stratification." (PMID 37891561, 2023). "Impaired glucose tolerance may be associated with more severe insulin resistance and reduced insulin secretion." (PMID 37841954, 2023). "Male mice lacking the Na+-K+-2Cl– cotransporter Slc12a2 (Nkcc1) specifically in insulin-secreting β-cells (Slc12a2βKO) have reduced β-cell mass and mild β-cell secretory dysfunction associated with overweight, glucose intolerance, insulin resistance, and metabolic abnormalities." (PMID 37819196, 2023). "Inhibition of Akt may cause insulin resistance because Akt is a major regulator of insulin action in muscle, fat, and liver." (PMID 37711887, 2023). "Second, insulin levels and insulin resistance were inadequately analyzed, even though diet and insulin resistance may be strongly associated with NAFLD in lean recipients." (PMID 36627697, 2023). "These signaling mechanisms are disrupted when skeletal muscle insulin resistance occurs, leading to a decrease in the insulin sensitivity and glucose absorption, which caused further damage to pancreatic β cells and impaired glucose tolerance, driving the development of T2DM." (PMID 37834276, 2023). "The significant correlations between visceral and total adipose tissue and the index of insulin resistance can be explained by the fact that the disproportionate accumulation of fat in the abdominal region is associated with reduced insulin-mediated glucose transport." (PMID 37109160, 2023). "In addition to its link with oxidative stress and inflammatory states, HSP60 deficiency causes insulin resistance and lessens the insulin‐sensitizing properties of adiponectin." (PMID 37583355, 2023). "However, a role for cocoa flavanols in reducing insulin resistance in the insulin-stimulated state, an important risk factor for cardiovascular disease, is unresolved." (PMID 36771271, 2023). "However, it is still unclear if insulin resistance first occurs due to any cause, then induces inflammation via the overproduction of free fatty acids, leading to further dysfunction of insulin signals associated with mitochondrial disorders." (PMID 37238649, 2023). "Insulin resistance causes elevated levels of insulin in circulation." (PMID 36408981, 2023). "However, given that TyG index and TG/HDL-c ratio are reliable measures of insulin resistance, the mediation effect of insulin on the association between LXA4 and the risk of T2DM development should be further elucidated." (PMID 36742389, 2023).